FOXO3 (forkhead box O3)
Diseases named in the same sentence as FOXO3 in open-access papers (continued):
Sharing a sentence is not in itself a finding about the gene and the disease.
prostate carcinoma (89 papers, 2008 to 2025). A carcinoma that arises from epithelial cells of the prostate gland. "FOXO3 is associated with various diseases, particularly in malignancy of various cancers such as breast, liver, colon, and prostate cancer." (PMID 33312341, 2020). "For instance, in prostate cancer increased cytoplasmic FOXO3 was associated with increased Gleason grade." (PMID 25202904, 2014). "Reduced FOXO3 activity has been linked to resistance to androgen deprivation therapy, whereas increased FOXO3 expression has demonstrated the ability to enhance the sensitivity of prostate cancer cells to this therapy." (PMID 38994962, 2024). "The modulation of FOXO3 activity and levels affects the growth and proliferation of numerous prostate cancer cell lines." (PMID 36768610, 2023). "Gene deletion of the tumor suppressors FOXO1 and FOXO3 is frequently observed in late-stage prostate cancer." (PMID 36768610, 2023). "An oral dose of 3–5 mg/kg withaferin A attenuated the activation of Akt and stimulated Forkhead Box-O3a (FOXO3a)-mediated prostate apoptotic response-4 (Par-4) activation, effectively inhibiting the tumor progression in prostate cancer cells." (PMID 37259311, 2023). "In vivo, the repression of FOXO3 activity leads to increased prostate cancer progression in the transgenic adenocarcinoma of the mouse prostate (TRAMP) mice." (PMID 36768610, 2023). "Silencing SGK1 inhibits MTOR signaling, providing conditions for FOXO3 phosphorylation, and subsequent induction of apoptosis and autophagy in prostate cancer cells." (PMID 35317831, 2022). "Mechanistically, SGK1 induces MTOR signaling to inhibit FOXO3 phosphorylation, leading to a decrease in apoptosis and autophagy in prostate cancer cells." (PMID 35317831, 2022). "Zhiyuan Shen and colleagues expressed that circular RNA Foxo3 reduction promotes chemoresistance and prostates cancer progression to Docetaxel65." (PMID 35676421, 2022). "It has been demonstrated that ERβ suppresses tumor growth and induces apoptosis by augmenting the transcription of the tumor-suppressor genes FOXO1 and FOXO3 in prostate cancer." (PMID 35574319, 2022). "FOXO3 is also targeted by miR-592 and miR-1307 to promote colorectal cancer metastasis and prostate cancer proliferation, respectively." (PMID 32372224, 2020). "FOXO3 has also been shown to bind and activate miR-34 for β-catenin inhibition which subsequently suppresses cell migration in prostate cancer." (PMID 32372224, 2020). "In prostate cancer, FOXO mutations are rare (<0.5% incidence), however FOXO1 and FOXO3 deep deletion is a frequent event, occurring in up to 15.2% and 13.4% of patients respectively." (PMID 32630372, 2020). "Other than inhibition of metastasis and cell proliferation, Dis induces apoptosis in prostate cancer cells through over expression of Bax, p27kip1 and Foxo3 and down regulation of Bcl-2 and c-Myc." (PMID 31295840, 2019). "Dis induces apoptosis in PC-3 human prostate cancer cells through overexpression of Bax, P27kip1 and Foxo3 and downregulation of Bcl-2 and c-Myc." (PMID 31295840, 2019). "Many such inhibitory activities of TADCs are driven by the transcription factor FOXO3; indeed, DCs isolated from prostate cancer patients display elevated levels of FOXO3 and effectively induce T cell tolerance." (PMID 26690204, 2015). "Likewise, in prostate cancer, FOXO3 has been identified as a partiCIPant in the control of androgen receptor signaling." (PMID 38994962, 2024). "miR-592 exhibits carcinogenic effects on prostate cancer cells by inhibiting Forkhead box O3A." (PMID 36381083, 2022). "A similar oncogenic role of Foxo3 has also been uncovered in prostate cancer and glioblastoma." (PMID 34555810, 2021).
prostate carcinoma (continued). "FOXO3 lies within the 6q21 locus that is frequently lost in prostate cancer, and reduced FOXO3 (also FOXO3a) activity via peptide driven inhibition is reported to accelerate prostate cancer progression in the transgenic adenocarcinoma mouse prostate (TRAMP) neuroendocrine prostate cancer model." (PMID 32630372, 2020). "In addition, the role of circRNA in drug resistance has been studied recently,reduction of circular RNA Foxo3 was found to promote prostate cancer progression and chemoresistance to docetaxel." (PMID 33262952, 2020). "Oral administration of WFA with a dose of 3–5 mg/kg inhibited the activation of Akt and facilitated the FOXO3a-(Forkhead box O3a) mediated activation of Par-4 (prostate apoptosis response-4) leading to delayed tumor progression in preclinical prostate cancer models." (PMID 31731424, 2019). "Over expression of miR-592 could promote the cell proliferation by downregulating the expression of FOXO3 involved in cell cycle process and promote the proliferation of prostate cancer cells." (PMID 29330490, 2018). "Apoptosis in prostate cancer might be also triggered by ERβ-induced increase in transcription of forkhead box O3 (FOXO3a)-transcription factor known as a tumour suppressor." (PMID 27186486, 2016). "Moreover, overexpression of FOXO3 induces apoptosis in the human prostate cancer cell line." (PMID 33312341, 2020). "Interestingly, FOXO3 can upregulate the expression of TRAIL in prostate cancer cells, and FOXO3 may be essential for the expression of DR5 in colon and live cancer cells." (PMID 27283899, 2016). "In bladder and prostate cancers, TP-mediated ERK activation phosphorylates the tumor suppressor protein forkhead box O3 (FOXO3), which is deacetylated by SIRT1, resulting in Skp2-mediated degradation." (PMID 36234768, 2022). "Paradoxically, the nuclear localization of FOXO3 was found to promote cell growth and tumor angiogenesis in neuroblastoma, and FOXO1 was shown to promote the transcription of VEGF-C in a prostate cancer cell line." (PMID 32629884, 2020). "Specifically, FOXO3 and FOXO1 are found to be deleted in approximately 15% to 20% of patients with prostate cancer." (PMID 32629884, 2020). "In prostate cancer cells, SIRT1/2 also promotes the multiubiquitination and proteasomal degradation of FoxO3 mediated by the E3 ubiquitin ligase subunit Skp2 by deacetylating FoxO3, thereby down‐regulating FoxO3 protein levels." (PMID 39778006, 2025). "Interestingly, similarly to FOXO3, SESN1 is located within the 6q21 locus that is commonly lost in prostate cancer." (PMID 32630372, 2020). "This phenomenon is not restricted to the AR-negative subtype, as GR can induce FOXO3 and GAS5 expression in AR-positive prostate cancer cells as well." (PMID 39027480, 2024).
colon carcinoma (85 papers, 2010 to 2025). "Avenanthramide C triggered cellular senescence in colon cancer cells by inhibiting the β-catenin-mediated transcription of miR-183/96/182 cluster, which was shown to be associated with the up-regulation of FOXO3." (PMID 39334758, 2024). "Oleanolic acid caused the apoptosis of HCT116 colon cancer cells by activating the p38 MAPK/FOXO3 pathway." (PMID 39334758, 2024). "Together, these data demonstrated that the loss of FOXO3 in PMNs is associated with human colon cancer progression, metastasis, and survival." (PMID 37298680, 2023). "Decreased expression of ST8Sia5 is associated with gene regulation by fork-head box O3 (FOXO3), the functional deficiency of which facilitates inflammation-mediated colon cancer growth linked to poor survival in patients." (PMID 36547200, 2022). "Next, we assessed publicly available transcriptomes from IBD and colon cancer patient cohorts to determine the significance of FOXO3-deficient macrophages in human colonic inflammation and tumorigenesis." (PMID 35323693, 2022). "Accordingly, it has been shown that cisplatin treatment causes a decrease in Akt-mediated FOXO3 phosphorylation in colon cancer cells, resulting in its nuclear translocation and activation." (PMID 29180117, 2018). "Proliferation of EGF treated colon cancer cells is mediated by loss of FOXO3 activity, and here we showed this pathway to be inhibited by genistein." (PMID 21639915, 2011). "The effect of genistein on proliferation stimulated by EGF-mediated loss of FOXO3 was examined in human colonic cancer HT-29 cells." (PMID 21639915, 2011). "Epidermal growth factor (EGF)-induced proliferation of colon cancer cells plays an important role in colon cancer progression and is mediated by loss of tumor suppressor FOXO3 activity." (PMID 21639915, 2011). "Additionally, FOXO3 can act as a tumor suppressor, and its loss correlates with advanced human colon cancer." (PMID 37298680, 2023). "Furthermore, Foxo3 deficiency accelerated tumor development in a colitis-associated colon cancer mouse model." (PMID 33795838, 2021). "The reduced expression of ST8Sia5 was linked to gene regulation by forkhead box O3 (FOXO3), the functional deficiency of which may facilitate inflammation-mediated colon cancer growth." (PMID 34975914, 2021). "We further investigated alternative mechanisms underlying FoxO3 modulation and asked whether the Akt/FoxO3 and myostatin/Smad3 axis were affected by implanted C26 colon carcinoma cells and JQ1 administration." (PMID 29167426, 2017). "The apoptosis effect of Aegiceras corniculatum leaf extract on human colon cancer cells was induced through the activation of the FOXO3 signaling pathway." (PMID 39334758, 2024). "Luteolin has antitumor activity in metastatic human colon cancer SW620 cells through an ERK/forkhead box O3a (FOXO3a)-dependent mechanism, and it has antimetastatic potential." (PMID 36768462, 2023).
colon carcinoma (continued). "Oleanolic acid induces both apoptosis and pro-survival mitophagy via the p38/forkhead box O3a (FOXO3a)/Sirt6 signaling in colon cancer cells, and also increases the chemosensitivity of colon cancer cells to 5-Fu." (PMID 38102686, 2023). "Based on our above findings, we sought to determine the significance of the loss of FOXO3 in PMNs in IBD and human colon cancer." (PMID 37298680, 2023). "Conversely, transcriptionally upregulating Gln synthetase, which converts Glu to Gln, enhanced LC3-II levels in a modified colon carcinoma cell line DLD1 that allowed for controlled activation of FOXO3." (PMID 36611873, 2022). "To test if DLG2 influenced these pathways we investigated the phosphorylation levels of AKT, FOXO3 and S6 in colon cancer cells." (PMID 35499706, 2022). "We found that transcriptomes of FOXO3-deficient macrophages represented similar alterations in pathways and upstream regulators as those seen in IBD (GSE4183) and colon cancer (GSE4183, GSE141174)." (PMID 35323693, 2022). "We validated select differentially expressed genes of FOXO3-deficient macrophages with established roles both in IBD and colon cancer." (PMID 35323693, 2022). "These DEGs were validated in FOXO3-deficient macrophages (vs WT) by qPCR, and their status was determined in publicly available transcriptomes of IBD and human colon cancer cohorts." (PMID 35323693, 2022). "Together, these data demonstrated that the macrophage-FOXO3 axis is associated with both human IBD and colon cancer." (PMID 35323693, 2022). "Conversely, it has been shown that the expression of functional FOXO3 enhanced the chemosensitivity of colon cancer cells to cisplatin treatment." (PMID 35910798, 2022). "Ultimately, we identified differentially expressed genes from FOXO3-deficient macrophages with established roles in both IBD and colon cancer, as well as novel genes whose roles in these colonic pathobiologies are not well understood." (PMID 35323693, 2022). "Here, we showed that treatment with UroA or UAS03 in 5FUR colon cancer cells significantly induced FOXO3 expression and downregulated FOXM1, which in turn is potentially responsible for downregulation of drug transporters." (PMID 35910798, 2022). "A study reported that genistein inhibits tumor growth and cell proliferation by downregulating the negative effect of epidermal growth factor (EGF) on the activity of forkhead box O3 (FOXO3) in a colon cancer model." (PMID 35883653, 2022). "Our studies suggest that FOXO3 expression is significantly downregulated in 5FUR colon cancer cells compared to parental colon cancer cells." (PMID 35910798, 2022). "Meanwhile, deregulation of FOXO3 levels has shown to differentially influence lymph node metastasis in invasive ductal carcinoma, TNBC and bladder carcinoma, finding that the interplay β-catenin-FOXO3 can also behave as a metastasis promoter in colon cancer." (PMID 34771514, 2021). "Analysis of a ChIP-seq dataset from the DLD1 colon carcinoma cells confirmed that FOXO3 binds to the promoter region of PERK gene." (PMID 32615282, 2020). "FOXO3 plays a pivotal role in inhibiting colon cancer cell proliferation, mainly through upregulation of the cell cycle inhibitor p27kip1113." (PMID 32029741, 2020). "The analysis revealed that FOXO3 binds to the promoter region of PERK gene in the DLD1 colon carcinoma cells." (PMID 31312024, 2019). "To this end, we first investigated if FOXO3 is recruited to PERK promoter in a previously published FOXO3 chromatin immunoprecipitation (ChIP)-Seq study in DLD1 colon carcinoma cells." (PMID 31312024, 2019). "In colon carcinoma cells, FOXO3 mediates the cytotoxic effect of cisplatin, through a mechanism involving FoxO3 dephosphorylation at threonine 32 and nuclear translocation, as well as induction of target genes, such as KIP and BIM." (PMID 30646603, 2019).
colon carcinoma (continued). "Studies have confirmed that miR182 is highly expressed in melanoma, colon cancer, and lung cancer and can promote cell migration and invasion by inhibiting FOXO3 and MITF." (PMID 31885738, 2019). "An impairment of the ability of cisplatin to activate FoxO signaling has been reported both for FoxO1 in ovarian carcinoma cells and FoxO3 in colon cancer cells." (PMID 30646603, 2019). "FOXO1, FOXO3, and FOXO4 were significantly underexpressed in tumour samples: in breast, bladder and colon tumours for FOXO1, in breast tumours for FOXO3, and in breast, bladder, and colon tumours for FOXO4." (PMID 29484124, 2018). "Conversely, functional FOXO3 has been reported to determine the sensitivity of colon cancer cells to cisplatin." (PMID 29180117, 2018). "We previously found that GEN-inhibited PI3K/Akt activation leads to inactivation of FOXO3, which negatively regulates proliferation in colon cancer cells." (PMID 29849534, 2018). "In the course of elucidating how REP1 functions in survival of colon cancer cells, we identified FOXO3 as a physical interactor for REP1 by Y2H." (PMID 28055019, 2017). "In colon carcinoma the interaction of FOXO3 with β-catenin confers resistance to FOXO3-induced cell death and instead leads to a highly metastatic phenotype." (PMID 27769056, 2016). "As further support for this potential role of direct FOXO3 transcriptional activation of Cluster Q and R genes, we analyzed a list of direct FOXO3 targets determined by ChIP-seq in a colon carcinoma cell-line." (PMID 26452208, 2015). "Recently it was also shown that FOXO3 interacts with β-catenin and that this interaction converts the transcriptional activity of FOXO3 to promote metastasis instead of apoptosis in colon cancer." (PMID 23801966, 2013). "A recent report suggested that genistein inhibited EGF-induced proliferation, which favors dephosphorylation and nuclear retention of FOXO3 in colon cancer cells." (PMID 23686257, 2013). "Active FOXO3 negatively regulates proliferation of colon cancer cells, and we showed that its inactivation is an essential step in EGF-mediated proliferation." (PMID 21639915, 2011). "We demonstrated that one of the anti-proliferative mechanisms of genistein in colon cancer cells is to promote FOXO3 activity by inhibiting EGF-induced FOXO3 phosphorylation (inactivation) via the PI3K/Akt pathway." (PMID 21639915, 2011). "This study demonstrated that genistein inhibits PI3K/Akt activation that leads to prevention of FOXO3 phosphorylation (inactivation) in colon cancer cells and revealed a new mechanism whereby genistein attenuates proliferation of colon cancer cells." (PMID 21639915, 2011). "Genistein inhibited EGF-induced proliferation, while favoring dephosphorylation and nuclear retention of FOXO3 (active state) in colon cancer cells." (PMID 21639915, 2011). "We have demonstrated that proliferation of colon cancer cells, stimulated with signals from EGFR, is mediated by loss of tumor suppressor FOXO3 activity." (PMID 21639915, 2011). "Additionally, a transcriptional signature representing FOXO3-deficient PMNs (PMN-FOXO3389) separated transcriptomes of affected tissue in IBD (p = 0.00018) and colon cancer (p = 0.0037) from control." (PMID 37298680, 2023). "Moreover, DEGs for FOXO3 KO PMNs shared upstream regulators with publicly available transcriptomes from several human colon cancer patient cohorts (GSE141174, GSE8671, GSE9348)." (PMID 37298680, 2023). "FOXO3 significantly decreased in colon cancer tissues compared to normal colon tissues." (PMID 35910798, 2022). "Importantly, the PI3K/mTOR inhibitor NVP-BEZ235 effectively reversed 5-FU resistance through inactivation of PI3K/Akt, which led to enhanced levels of FOXO3 in colon cancer cells." (PMID 35910798, 2022).